RN7SKP18 (RN7SK pseudogene 18)
Gene: Miscellaneous RNA gene on chromosome 6 (117,299,364 to 117,299,638, forward strand). Ensembl gene ENSG00000251814.
Homologues: Orthologues: chimpanzee 7SK (98% identical). Paralogues in human: RN7SKP51 (81% identical), RN7SKP77 (69% identical), RN7SKP240 (68% identical), RN7SKP251 (68% identical), RN7SKP189 (68% identical), RN7SKP72 (67% identical), RN7SKP9 (67% identical), RN7SKP90 (67% identical), RN7SKP124 (67% identical), RN7SKP127 (67% identical), RN7SKP176 (67% identical), RN7SKP217 (67% identical), and 284 more.